NEB (nebulin)
Description:
This giant muscle protein may be involved in maintaining the structural integrity of sarcomeres and the membrane system associated with the myofibrils. Binds and stabilize F-actin.
Synonyms: NEB177D; AMC6; NEM2
Tractability: PROTAC: ubiquitination databases record sites on it; its protein half-life has been measured.
Gene: Protein-coding gene on chromosome 2 (151,485,336 to 151,734,487, reverse strand). Ensembl gene ENSG00000183091.
Subcellular location: Cytoplasm, myofibril, sarcomere; Cytoplasm, cytoskeleton
Pathways (Reactome):
Muscle contraction: Striated Muscle Contraction
Gene Ontology:
Molecular function: protein binding; actin filament binding; structural constituent of muscle; actin binding
Biological process: cardiac muscle thin filament assembly; muscle organ development; regulation of actin filament length; somatic muscle development
Cellular component: extracellular exosome; Z disc; actin cytoskeleton; cytosol; cytoplasm; cytoskeleton; sarcomere
Genetic constraint (gnomAD): Loss-of-function variants: 372 observed, 679.42 expected, observed/expected ratio (o/e) 0.55, 90% interval 0.5 to 0.6. The upper end of that interval is the gene's LOEUF score, 0.6, which puts it in group 2 of 6, group 1 being the genes least tolerant of losing a copy. Missense variants: 7,406 observed, 7,955.5 expected, observed/expected ratio (o/e) 0.93, 90% interval 0.91 to 0.95. Synonymous variants: 2,590 observed, 2,760 expected, observed/expected ratio (o/e) 0.94, 90% interval 0.91 to 0.97.
Gene-disease validity (ClinGen):
ClinGen rates the evidence that NEB causes each of these diseases.
nemaline myopathy 2 (autosomal recessive): Definitive.
autosomal dominant nebulin-related myopathy (autosomal dominant): Moderate. Any myopathy in which an autosomal dominantly inherited genetic variation in the NEB gene causes disease via a dominant-negative mechanism.
Homologues: Orthologues: chimpanzee NEB (89% identical), rat Neb (82% identical), mouse Neb (82% identical), rabbit NEB (74% identical), pig NEB (73% identical), dog NEB (72% identical), guinea pig NEB (69% identical), tropical clawed frog neb (54% identical), zebrafish neb (43% identical), Caenorhabditis elegans ltd-1 (1% identical), Drosophila melanogaster Hil (1% identical). Paralogues in human: NRAP (8% identical), NEBL (4% identical), LASP1 (1% identical), KY (1% identical).
Diseases named in the same sentence as NEB in open-access papers:
NEB is named in the same sentence as 72 diseases in open-access papers, as found by Europe PMC text mining. Sharing a sentence is not in itself a finding about the gene and the disease. The quoted sentences say what the papers report.
nemaline myopathy (69 papers, 2010 to 2025). Nemaline myopathy (NM) encompasses a large spectrum of myopathies characterized by hypotonia, weakness and depressed or absent deep tendon reflexes, with pathologic evidence of nemaline bodies (rods) on muscle biopsy. "We report a case of nemaline myopathy with marked asymmetry and predominantly distal lower limb muscle weakness caused by suspected biallelic variants in the NEB gene." (PMID 40091977, 2025). "The proband of Family 1 was also compound heterozygous for two recessive variants in NEB, resulting in a concomitant nemaline myopathy." (PMID 41313434, 2025). "Muscle biopsy revealed pathological changes consistent with nemaline myopathy, and suspected biallelic variants in the nebulin (NEB) gene, NM_001271208.1:c.24684G>C p.(Ser8228Ser) and c.23847+164A>G were identified." (PMID 40091977, 2025). "According to OMIM, pathogenic variants in NEB cause nemaline myopathy and arthrogryposis multiplex congenita; both diseases are associated with AR inheritance." (PMID 40525497, 2025). "This revealed biallelic pathogenic variants in the NEB gene, resulting in a diagnosis of nemaline myopathy." (PMID 40524706, 2025). "Lastly, while mild muscle involvement is recognized in GD, the presentation of florid limb-girdle myopathy in one patient and disuse osteoporosis led to the identification of variants in the NEB gene associated with nemaline myopathy." (PMID 41282474, 2025). "We discussed a case of nemaline myopathy with suspected biallelic NEB variants characterized by pronounced asymmetric, distal-dominant muscle atrophy and weakness, underscoring the importance of recognizing this phenotype to enhance diagnostic accuracy." (PMID 40091977, 2025). "Biallelic pathogenic variants in the nebulin (NEB) gene lead to the congenital muscle disease nemaline myopathy." (PMID 39764134, 2024). "The distribution of type I and type II muscle fibers were significantly abnormal in patients with nemaline myopathy caused by NEB gene, however, it was basically normal in patients with nemaline myopathy caused by TPM3 gene and ACTA1 gene." (PMID 37525074, 2024). "Nemaline myopathy (NM) was diagnosed with the help of clinical exome sequencing, which showed a compound heterozygous mutation with a novel variant in the nebulin (NEB) gene." (PMID 39099920, 2024). "Recessive mutations in Kelch proteins (KLHL40, KLHL41) are thought to cause nemaline myopathies by impairing efficient polyubiquitination of their thin filament substrates (NEB, LMOD3, NRAP), leading to their reduced turnover." (PMID 39501809, 2024). "Pathogenic variants in the NEB gene account for approximately 35% of nemaline myopathies, which are usually inherited recessively." (PMID 38634969, 2024). "Mutations in NEB are known to cause nemaline myopathy (NM; MIM IDs: NEM2 #256030) and other congenital myopathies." (PMID 35576196, 2022). "Loss of nebulin causes nemaline myopathy in humans, a condition associated with severe muscle weakness." (PMID 35893068, 2022). "Many forms of nemaline myopathy arise from mutations in nebulin, a giant protein that winds around the actin filaments in the sarcomeres of skeletal muscle." (PMID 35328477, 2022). "It was reported that the mutation of NEB was associated with many diseases, such as nemaline myopathy and fetal akinesia deformation sequence/arthrogryposis multiplex congenita." (PMID 36250027, 2022). "Mutational hotspot c.21522 + 3A > G in NEB gene was discovered in nemaline myopathy patients in China and three mutational sites in NEB gene were reported which haven't been discovered before." (PMID 33742414, 2022). "Mutations in nebulin gene (NEB) are known to be responsible for about 50% of nemaline myopathy cases." (PMID 34211429, 2021). "It has been shown that thin filament dysregulation resulting of a mutation in NEB, can contribute to muscle weakness in patients with nemaline myopathy." (PMID 34211429, 2021).
nemaline myopathy (continued). "Biallelic pathogenic variants in NEB cause autosomal recessive, nemaline myopathy 2, which accounts for about 50% of cases of nemaline myopathy." (PMID 33827624, 2021). "These phenotypes are likely caused by the loss of full-length nebulin, creating an environment more like that of nemaline myopathy." (PMID 31992366, 2020). "The major cause of nemaline myopathy are mutations in NEB (nebulin) accounting for more than 50% of cases." (PMID 32456280, 2020). "Of these, the findings of two heterozygous NEB variants prompted the muscle biopsy to demonstrate changes related to nemaline myopathy as a possible diagnosis." (PMID 32684384, 2020). "Eight are associated with the thin filaments, three are thought to participate in nebulin stabilization or turnover, and two are more peripherally associated with the development of nemaline myopathy." (PMID 31992366, 2020). "Human NEB-nemaline myopathy patients with various NEB mutations produced 7–69% of the force measured in control patients." (PMID 31982973, 2020). "Nemaline myopathy (NEM) is a congenital neuromuscular disorder primarily caused by nebulin gene (NEB) mutations." (PMID 31721788, 2019). "NEB mutations are usually recessively inherited, but recently, the first dominantly inherited mutation was identified in NEB, causing a distal form of nemaline myopathy." (PMID 31228046, 2019). "Mutations in nebulin, encoding a large sarcomeric protein required for thin filament function, are responsible for approximately 50% of nemaline myopathy cases." (PMID 29848386, 2018). "Here, we have characterized and validated a new NEB nemaline myopathy model containing a mutation within the super repeat region of the nebulin protein, causing nonsense mediating decay of the resulting transcript." (PMID 29848386, 2018). "Mutations in the NEB gene have been identified as a cause of nemaline myopathy, an autosomal recessive disorder." (PMID 29297313, 2017). "A common cause of nemaline myopathy is mutations in the gene that encodes the nebulin protein, which serves as a scaffold for the sarcomere assembly." (PMID 28826497, 2017). "To investigate the origin of nemaline bodies and to uncover the cause of skeletal muscle weakness, we developed overexpression and loss-of-function zebrafish models for ACTA1-related and a loss-of-function model for NEB-related nemaline myopathy." (PMID 25931053, 2015). "Family 13DG0975 was found to harbor a homozygous stopgain mutation in NEB (c.21076C > T:p.R7026X), which predicts a severe form of nemaline myopathy, which has rarely been reported to cause NIHF." (PMID 26036949, 2015). "Nemaline myopathy due to NEB mutations has been found to occur in association with ophthalmoplegia, a condition characterized by weakness or paralysis of one or more extraocular muscles, which are responsible for eye movement." (PMID 25938837, 2015). "The theory that nebulin is not involved in cardiac myofibril organization is further supported by the fact that several missense mutations in nebulin have been implicated in nemaline myopathy in skeletal muscle." (PMID 26798563, 2014). "KLHL41 interacts with nebulin and co-localizes with actin, mutations of which cause approximately 65% to 70% of all known mutations in patients affected with nemaline myopathy." (PMID 24959344, 2014). "KLHL41 also interacts with nebulin, a known causative gene of nemaline myopathy, by protein-protein interactions and is co-localized with actin at the tips of pseudopodia in fibroblasts." (PMID 24959344, 2014). "In addition, recessive NEB variants have been identified in patients with congenital myopathy with cap-like structures and nemaline bodies, core-rod myopathy, and lethal neonatal arthrogryposis multiplex congenita-6 (AMC6, MIM ID #619334)." (PMID 40517164, 2025).
nemaline myopathy (continued). "It has also been implicated in the regulation of thin filament length (TFL), as reduced levels of nebulin protein have been associated with shortened TFL in patients with NEB-related nemaline myopathy, as well as in nebulin-deficient mouse models, zebrafish, and chick skeletal myocytes." (PMID 38634969, 2024). "Nemaline myopathy is most commonly caused by recessive NEB mutations." (PMID 39501809, 2024). "Recessive mutations in NEB account for > 50% of cases of nemaline myopathy." (PMID 39764134, 2024). "However, a recent study identified the first dominantly inherited pathogenic variant in NEB, leading to a distal form of nemaline myopathy." (PMID 38634969, 2024). "Interestingly, mutations in KLHL41 and NEB are associated with subtypes of nemaline myopathy, further connecting these proteins to myodegeneration in SBMA." (PMID 38973610, 2024). "Homozygous intronic mutations in intron 144, which created an alternative donor (5’) splice site in exon 144 and a decrease in NEB expression, were found causal in a case of a 6-year-old boy with general muscle weakness and nemaline bodies consistent with nemaline myopathy." (PMID 37576554, 2023). "In detail, the NEB mutation may cause Nemaline myopathy, and POLRMT is a key enzyme for transcription of the mitochondrial genome." (PMID 37860673, 2023). "Mutations in nebulin are known to cause nemaline myopathy and other congenital myopathies." (PMID 35576196, 2022). "There are nemaline myopathies due to mutations in proteins other than nebulin." (PMID 35328477, 2022). "While in our research, 5 out 6 unrelated nemaline myopathy patients with NEB mutations harbored this mutational site, which reminded us that this mutational site might be a mutational hotspot for nemaline myopathy patients in China." (PMID 33742414, 2022). "Dominant mutations in ACTA1 and TPM3 are most frequently associated with nemaline myopathy characterized by early onset and respiratory insufficiency, while recessive forms of nemaline myopathy are most frequently associated with mutations in the nebulin gene (NEB)." (PMID 35980353, 2022). "In this study, we present a novel variant in the NEB gene of a young boy with nemaline myopathy." (PMID 34211429, 2021). "Indeed, finding of variants affecting the alternative splicing of nebulin will make it possible to know more about the function of the different isoforms and allow us to clarify their respective implications in congenital nemaline myopathy." (PMID 34211429, 2021). "A distal phenotype in NEB-associated nemaline myopathy and DNM2-associated centronuclear myopathy seems to be more common in late-onset CMs, and similarly a scapuloperoneal pattern may be also observed in late onset ACTA-1-related nemaline myopathy." (PMID 32456280, 2020). "Nemaline myopathy due to mutations in NEB could have explained many of the clinical features of this case, including proximal and distal weakness and wasting, facial weakness, and respiratory muscle weakness, although ophthalmoplegia is unusual." (PMID 32684384, 2020). "Indeed it has been shown that FASTAs increase force at submaximal activation levels in type II skeletal muscle fibers from nebulin-deficient mice and nemaline myopathy patients." (PMID 31721788, 2019). "However, it has a good potential to bring relief in nebulin-based nemaline myopathy patients, not only because of their type I predominance but also because nebulin deficiency appears to increase the effectiveness of OM." (PMID 31721788, 2019). "Mutations in the nebulin gene NEB are a common cause of nemaline myopathy." (PMID 30356055, 2018). "Beyond histologically defined nemaline myopathy, pathogenic variants in NEB may lead to additional clinical manifestations, including core-rod myopathy, distal nebulin myopathy without nemaline rods, lethal multiple pterygium syndrome, and a dominant form of distal nemaline/cap myopathy." (PMID 40091977, 2025).
nemaline myopathy (continued). "Nemaline myopathy (NM) caused by mutations in the gene encoding nebulin (NEB) accounts for at least 50% of all NM cases worldwide, representing a significant disease burden." (PMID 32066503, 2020). "For example, Nebulin is a large actin-binding protein and the main cause of nemaline myopathy (NEM)." (PMID 32258109, 2020). "In addition to interacting with actin, the central, super-repeat region of the molecule also binds directly to myosin and tropomyosin and altered binding affinity for these proteins has been found when investigating nebulin protein affected by nemaline myopathy causing NEB mutations." (PMID 31982973, 2020). "Compound-heterozygous mutations in the nebulin gene (NEB) cause typical nemaline myopathy (NM), a muscle disorder characterized by muscle weakness with limited treatment options." (PMID 32483185, 2020). "Respiratory failure due to diaphragm dysfunction is considered a main cause of death in nemaline myopathy (NM) and we studied both isometric force and isotonic shortening of diaphragm muscle in a mouse model of nebulin-based NM (Neb cKO)." (PMID 31658633, 2019). "However, mutations in NEB cause some cases of the autosomal recessive disorder nemaline myopathy." (PMID 25938837, 2015). "The most frequently implicated genes include NEB and ACTA1 in nemaline myopathies and RYR1 in core myopathies." (PMID 40525497, 2025). "The majority of these cases encompassed pathogenic RYR1 variants in core myopathy, NEB and ACTA1 in nemaline myopathy, and pathogenic MTM1 variants in CNM." (PMID 38982518, 2024). "Collectively, these findings indicate that inhibiting myostatin can mitigate the muscle deficits in nebulin-based typical nemaline myopathy, potentially serving as a much-needed therapeutic option." (PMID 37894805, 2023). "Similar to mutations in the NEB exon 143-144 region, KLHL40 deficiency is associated with nemaline myopathy." (PMID 37576554, 2023). "And one nonsense change c.4417C > T and two splice changes c.23233-1G > T/c.5343 + 1G > A were newly discovered nucleotide changes according HGMD database for NEB gene in nemaline myopathy patients." (PMID 33742414, 2022). "Such a discovery of variants in this gene will allow a better understanding of the involvement of nebulin in neuromuscular diseases and help find new treatments for the nemaline myopathy." (PMID 34211429, 2021). "There were six large homozygous blocks, including well-known nemaline myopathy genes NEB: 1p13.3-q25.3; 2q11.2-q31.1; 5p13.2-q14.1; 11p14.2-p13; 16q22.1-q23.2; 21q11.2-q21.1." (PMID 34211429, 2021). "Other skeletal muscle diseases with altered nuclear spacing notably include those caused by mutations in genes encoding nuclear envelope proteins, dynamin 2 (centronuclear myopathy) and skeletal muscle actin/nebulin (nemaline myopathy)." (PMID 33076971, 2020). "Additional studies must also be performed to account for the fact that patients with nemaline myopathy often retain some full-length nebulin." (PMID 31992366, 2020). "Of these genes, the thin filament regulatory protein nebulin is estimated to be responsible for approximately 50% of all observed cases of nemaline myopathy." (PMID 31992366, 2020). "In turn, KLHL40 is suggested to stabilize nebulin and Leimodin 3 (LMOD3, another protein implicated in nemaline myopathy) by acting like a chaperone and maintaining proper folding of these two proteins during muscle contraction." (PMID 32660935, 2020). "Kelch-like family member 41, KLHL41, was selected for its role in nebulin stabilization as well as possible ubiquitination processes in nemaline myopathy." (PMID 31992366, 2020). "NEB is a special case that is camouflaged by itself (rather than another gene), and is associated with 24 diseases in the HGMD, including nemaline myopathy, a hereditary neuromuscular disorder." (PMID 31104630, 2019).